FGF5 (fibroblast growth factor 5)
Diseases named in the same sentence as FGF5 in open-access papers (continued):
Sharing a sentence is not in itself a finding about the gene and the disease.
tumor (continued). "Third and finally, elevated expression of Sox2 in the majority of castration-resistant metastases and tumor xenografts implicates a role for Sox2 and its target genes such as FGF5 in promoting castration resistance." (PMID 23326489, 2013). "Notably, FGF5 expression was significantly higher in tumor samples compared to normal tissues, whereas its methylation levels were markedly reduced in NPC patients with distant metastases." (PMID 40001587, 2025). "FGF5 contributes to NPC progression by promoting tumor cell invasion and metastasis, and its methylation status may serve as a prognostic marker for distant metastasis in NPC patients." (PMID 40001587, 2025). "The hypomethylation of FGF5 may facilitate its overexpression, contributing to the tumor’s aggressive behavior and ability to evade treatment-induced apoptosis." (PMID 40001587, 2025). "Even if tumor-cell-derived FGF5 could be downregulated by cisplatin or radiation, CAFs could continue to produce FGF5, thereby promoting tumor cell survival and migration." (PMID 40001587, 2025). "The suppressive effect of DDP on tumor growth was counteracted by FGF5 recombinant protein." (PMID 38637504, 2024). "In BC, tumor cells promote the expression of MEKK1 in CAFs by secreting FGF5." (PMID 37868988, 2023). "Fibroblast growth factor 5 (FGF5) possess broad mitogenic and cell survival activities, and are involved in a variety of biological processes, including embryonic development, cell growth, morphogenesis, tissue repair, tumor growth and invasion." (PMID 37471354, 2023). "Finally, we examined the importance of tumor-derived FGF-5 to CCL5 expression in mammary fibroblasts." (PMID 33868996, 2021). "FGF5 had relationships with embryonic development, cell growth, morphogenesis, tissue repair, tumor growth, and invasion, and it may be a potential candidate gene associated with CW." (PMID 31805716, 2019). "Taken together, our data indicated that miR-567 may function as a tumor suppressor by negatively regulating FGF5 and be potential therapeutic targets for the treatment of OS." (PMID 29743851, 2018). "Since VM21-FGF5 cells secrete an enhanced amount of FGF5, the tumor microenvironment could also contribute to the increased growth of VM21-FGF5 tumors." (PMID 29152117, 2017). "In a previous study, we demonstrated oncogenic activity of FGF5 in astrocytic brain tumors, which could be attributed to both autocrine effects on the tumor cells as well as paracrine effects on endothelial cells." (PMID 29152117, 2017). "Immunohistochemical (IHC) staining of formalin-fixed paraffin embedded (FFPE) tumor sections from the excised xenotransplanted tumors confirmed overexpression of FGF5 on the protein level in VM21-FGF5 compared to VM21-GFP cells and demonstrated the specificity of the antibody on paraffin sections." (PMID 29152117, 2017). "However, recent studies have highlighted that CAFs, which are more resistant to radiation and chemotherapy, may serve as an important source of FGF5 in the tumor microenvironment." (PMID 40001587, 2025). "Notably, we observed that FGF5 expression in tumor cells is downregulated after irradiation treatment, yet its overexpression or re-expression significantly enhances tumor cell migration, highlighting its complex involvement in NPC biology and treatment resistance." (PMID 40001587, 2025). "Finally, concerning the tumor cells themselves, there are some lines of evidence that the cells stimulate their migratory activity in an autocrine manner, including interleukin-1α and β, as well as FGF-5, which are released by the PC-3 cells, too." (PMID 20626867, 2010). "Compared to tumors with diploid/normal copy number, levels of B cell and CD4+ T cell infiltration were reduced in tumor samples with arm-level deletion of BTLA, CLDN11, and FGF5." (PMID 39796775, 2025).
tumor (continued). "In our study, we performed methylation sequencing on tumor samples from NPC patients who had undergone radiotherapy, identifying significant upregulation of FGF5 gene expression in those with distant metastasis." (PMID 40001587, 2025). "The mRNA level of CR2, INSL4, FGF5, RAET1L and TNFRSF13B was upregulated in LUAD tumor tissues compared with paired normal tissues whereas AGER was downregulated." (PMID 36294477, 2022). "WT1, COL11A1, FGF5, and IGFL2 were up-regulated in tumor tissues, while GFAP and CD300LG were down-regulated." (PMID 33987034, 2021). "In detail, FGF1 and FGF10 were downregulated in most of the tumor types whereas FGF3, FGF5, FGF11, FGF19, FGF20, and FGF21 were upregulated in most of the tumor types." (PMID 32596330, 2020). "Next, we performed FGF5 and FGF7 IHC staining that revealed downregulation of these key FGF pathway molecules in anti-NCAM traeted tumor samples." (PMID 31477684, 2019). "There was tumor-specific basal heterogeneity, but there was a trend towards an increase in the wound signature mRNAs especially in the Meso PCTS; all but COL3A1 genes were increased, but only FGF5 reached significance." (PMID 38744944, 2024). "Additionally, the role of CAFs as a potential source of FGF5 in the tumor microenvironment warrants further investigation, as targeting CAF-derived FGF5 may provide a novel strategy to overcome treatment resistance in NPC." (PMID 40001587, 2025). "Increased FGF‐5 levels may promote oncogenic signalling pathways, such as the MAPK and PI3K‐Akt pathways identified in our KEGG pathway analysis, further contributing to tumour growth and resistance to immunotherapy." (PMID 40078069, 2025).
cardiovascular diseases (6 papers, 2020 to 2025). "Previous MR studies have demonstrated that FGF-5 is causally associated with cardiovascular disease risk, which is consistent with the results of the present study." (PMID 40184136, 2025). "We detected a cis signal for the FGF5 level and associated variants in the region, which overlapped with previous GWAS findings for cardiovascular diseases and medications used to treat them." (PMID 38565889, 2024). "We also demonstrated confirmatory evidence for the causal role of four further proteins (FGF5, IL6R, LPL, LTA) in cardiovascular disease risk." (PMID 32628676, 2020).
infection (1 paper, 2025). The state of being infected such as from the introduction of a foreign agent such as serum, vaccine, antigenic substance or organism. "The protein expression of seven proteins (CD8A, ST1A1, AXIN1, FGF-5, MMP-10, HGF, SIRT2) was significantly decreased and the protein expression of two proteins (MMP-1, TNFRSF9) was significantly increased in caspase-1-deficient cells compared to Cas9 cells following HK1651 infection." (PMID 40137780, 2025).
FGF5 also shares sentences with these, for which no sentence is quoted: Alzheimer disease (2 papers); cholangiocarcinoma (2); ischaemic stroke (2); adenoma (1); angina (1); Breast Tumor (1); coronary atherosclerosis (1); esophageal squamous cell carcinoma (1); frontotemporal dementia (1); gastric cancer (1); gestational diabetes (1); glioma (1); gout (1); graft versus host disease (1); Hydrocephalus (1); hypercortisolism (1); hypothyroidism (1); immune system disease (1); inflammatory bowel disease (1); lung adenocarcinoma (1); malignant pleural mesothelioma (1); metabolic syndrome (1); metastatic melanoma (1); migraine (1); multiple system atrophy (1); muscular dystrophy (1); myocardial infarction (1); nevus (1); non-alcoholic steatohepatitis (1); osteoporosis (1).
A further 11 diseases each share a sentence with FGF5 in 1 paper.